SMO (smoothened, frizzled class receptor)
Description:
G protein-coupled receptor, which transduces the smoothened signaling pathway. Activated by cholesterol in response to hedgehog (DHH, IHH or SHH) morphogens. In absence of hedgehog, SMO is inactivated by patched protein (PTCH1 or PTCH2), which prevents SMO access to cholesterol. In response to hedgehog-binding to pathched, inhibition is relieved, promoting SMO translocation to primary cilium and activation by cholesterol: cholesterol causes a conformation change that triggers signaling via G protein G(i), mediating inhibition of adenylate cyclase activity and decreassed production of cAMP. Decreased cAMP levels then inhibit protein kinase A (PKA) and promote release of GLI (GLI1, GLI2 and GLI3) transcription factors, which activate expression of target genes. Active SMO also directly inhibits PKA by sequestering its catalytic subunit, PRKACA, at the cell membrane, preventing PRKACA-mediated phosphorylation and subsequent processing of GLI transcription factors. Active SMO also promotes the removal of GPR161, a key inhibitor of the smoothened signaling pathway, from primary cilia (By similarity).
Synonyms: SMOH; FZD11; CRJS; Gx; PHLS
Tractability: Small molecule: an approved drug acts on it; a structure with a bound ligand is known; a high-quality ligand is known; it belongs to a druggable protein family. Antibody: its Gene Ontology location is reachable by antibodies, with high confidence; UniProt places it where antibodies can reach, with medium confidence; UniProt predicts a signal peptide or a membrane-spanning region. PROTAC: a small molecule that binds it is known.
Target class: Membrane receptor; Smoothened receptor (frizzled family GPCR); Frizzled family G protein-coupled receptor
Chemical probes: CHEMBL2059863, CYCLOPAMINE (high quality), PD082456
Gene: Protein-coding gene on chromosome 7 (129,188,511 to 129,213,546, forward strand). Ensembl gene ENSG00000128602.
Subcellular location: Cell membrane; Cell projection, cilium membrane
Subcellular location (Human Protein Atlas): Golgi apparatus; Plasma membrane; Primary cilium
Pathways (Reactome):
Signal Transduction: Activation of SMO; Class B/2 (Secretin family receptors); Hedgehog 'off' state; Hedgehog 'on' state
Organelle biogenesis and maintenance: BBSome-mediated cargo-targeting to cilium
Gene Ontology:
Molecular function: cholesterol binding; G protein-coupled receptor activity; patched binding; protein binding; protein sequestering activity; oxysterol binding; protein kinase A catalytic subunit binding; transmembrane signaling receptor activity
Biological process: adenylate cyclase-inhibiting G protein-coupled receptor signaling pathway; contact inhibition; positive regulation of cell migration; positive regulation of gene expression; smooth muscle tissue development; smoothened signaling pathway; cellular response to cholesterol; central nervous system development; commissural neuron axon guidance; determination of left/right asymmetry in lateral mesoderm; forebrain morphogenesis; heart looping; mesenchymal to epithelial transition involved in metanephric renal vesicle formation; midgut development; pattern specification process; positive regulation of branching involved in ureteric bud morphogenesis; positive regulation of transcription by RNA polymerase II; regulation of heart morphogenesis; somite development; ventral midline determination; cell surface receptor signaling pathway; negative regulation of DNA-templated transcription; positive regulation of DNA-templated transcription; positive regulation of multicellular organism growth; positive regulation of organ growth; and 3 more
Cellular component: caveola; cilium; extracellular exosome; Golgi apparatus; non-motile cilium membrane; plasma membrane; ciliary membrane; ciliary tip; dendrite; endocytic vesicle membrane; 9+0 non-motile cilium; centriole; cytoplasm; endoplasmic reticulum; endoplasmic reticulum-Golgi intermediate compartment; late endosome; membrane; plasma membrane bounded cell projection
Genetic constraint (gnomAD): Loss-of-function variants: 38 observed, 70.52 expected, observed/expected ratio (o/e) 0.54, 90% interval 0.41 to 0.71. The upper end of that interval is the gene's LOEUF score, 0.71, which puts it in group 2 of 6, group 1 being the genes least tolerant of losing a copy. Missense variants: 840 observed, 964.98 expected, observed/expected ratio (o/e) 0.87, 90% interval 0.82 to 0.92. Synonymous variants: 392 observed, 383.72 expected, observed/expected ratio (o/e) 1.02, 90% interval 0.94 to 1.11.
Gene-disease validity (ClinGen):
ClinGen rates the evidence that SMO causes each of these diseases.
mosaic SMO syndrome (autosomal dominant): Definitive. A somatic mosaic condition caused by a postzygotic mutation (c.1234 C>T p.Leu412Phe) in the SMO gene.
congenital hypothalamic hamartoma syndrome (autosomal recessive): Moderate. Hypothalamic hamartomas (HH) are rare, tumor-like malformations that occur during fetal development and are present at birth.
Cancer hallmarks: change of cellular energetics; proliferative signalling (promotes); angiogenesis (promotes); escaping programmed cell death (promotes); tumour promoting inflammation; invasion and metastasis (promotes)
Homologues: Orthologues: chimpanzee SMO (99% identical), macaque SMO (99% identical), dog SMO (96% identical), guinea pig SMO (95% identical), pig SMO (95% identical), rabbit SMO (94% identical), mouse Smo (93% identical), rat Smo (93% identical), tropical clawed frog smo (70% identical), zebrafish smo (69% identical), Drosophila melanogaster smo (37% identical). Paralogues in human: FZD8 (21% identical), FZD3 (21% identical), FZD1 (20% identical), FZD6 (20% identical), FZD7 (20% identical), FZD2 (19% identical), FZD5 (19% identical), FZD9 (19% identical), FZD10 (18% identical), FZD4 (18% identical), SFRP1 (9% identical), SFRP5 (8% identical), and 3 more.
Diseases named in the same sentence as SMO in open-access papers:
SMO is named in the same sentence as 198 diseases in open-access papers, as found by Europe PMC text mining. Sharing a sentence is not in itself a finding about the gene and the disease. The quoted sentences say what the papers report.
medulloblastoma (133 papers, 2009 to 2026). A malignant, invasive embryonal neoplasm arising from the cerebellum. "Mutations in the PTCH1 gene (encoding Patched-1 receptor) and the SMO gene (encoding the Smoothened homolog) lead to abnormal pathway activation, resulting in medulloblastoma and basal cell carcinoma." (PMID 40115023, 2025). "Resistance to SMO inhibition was first described in 2009 and the patient with medulloblastoma had mutations in the SMO gene." (PMID 40094009, 2025). "The GPCR PTCH and SMO are important targets for regulation, as inactivating PTCH mutations or activating SMO mutations are linked with medulloblastoma and basal cell carcinoma." (PMID 40969301, 2025). "Hyperactivation of the SHH cascade in basal cell carcinoma and medulloblastoma is mainly due to repressive mutations in PTCH or activating mutations in SMO." (PMID 37149646, 2023). "In this context, Tumor-associated macrophages (TAMs) were noticed to play a cancer-promoting role in medulloblastomas belonging to the SHH subgroup with SMO mutations." (PMID 37568705, 2023). "In this context, the most studied inhibitors, i.e., SMO inhibitors, have shown encouraging results for the treatment of basal cell carcinoma and medulloblastoma, both tumour types often associated with mutations that lead to the activation of the pathway." (PMID 36765685, 2023). "Data from both medulloblastoma cells and allograft mouse models provide additional evidence that the mutation of SMO at this specific aspartic acid residue can confer resistance to vismodegib." (PMID 35163655, 2022). "Smoothened (SMO) is another candidate gene frequently harboring somatic mutations in medulloblastoma tumors but also affecting the germline in adult medulloblastoma patients, potentially opening the door for target therapies such as SMO inhibitors." (PMID 34888241, 2021). "Among the SHH pathway genes, PTCH1 was mutated in 36% (12/33) of adult SHH medulloblastomas, and SMO was mutated in 27% (9/33)." (PMID 33172502, 2020). "Missense mutations in SMO have also been identified as a cause for acquired drug resistance after continuous treatment of HH-induced murine medulloblastoma with sonidegib." (PMID 30991683, 2019). "Mutations in Hh pathway components, including Ptc1 and SMO, that lead to pathway activation have been linked to basal cell carcinoma and medulloblastoma." (PMID 31117185, 2019). "Inactivating mutations in PTCH, SUFU, and GNAS or activating mutations of SMO, indicative of Hedgehog pathway misregulation, have been described for sporadic basal cell carcinoma and medulloblastoma tumors." (PMID 30884815, 2019). "The critical role of PI3K/AKT in SMO-independent activation of GLI is underlined by the finding that medulloblastoma cells resistant to SMOi display upregulation of PI3K/AKT signaling and sensitivity to PI3K targeting." (PMID 30991683, 2019). "In general, canonical activation of HH-GLI signaling occurs in cancers with mutations in PTCH1 and SMO, such as BCC and SHH-type medulloblastoma, most of which are sensitive to SMO antagonists." (PMID 31244888, 2019). "For one male patient with recurrent medulloblastoma and SMO mutation, vismodegib was considered as targeted therapy in our analysis." (PMID 31882734, 2019). "Accordingly, transgenic mice with loss of PTCH1 or gain of function of SMO develop BCCs and medulloblastomas." (PMID 29695137, 2018). "The mutations in SMO were firstly described in basal cell carcinoma and recently in brain tumors, meningioma and medulloblastoma." (PMID 27164089, 2016). "SMO alterations leading to the activation of the SHH pathway in medulloblastoma are generally related to activating mutations." (PMID 27825128, 2016).
medulloblastoma (continued). "Activating mutations in SMO have also been recognized in sporadic cases of medulloblastoma and SMO is overexpressed in many other cancers." (PMID 26633513, 2015). "This is due to selection of tumor cells with a corresponding mutation in SMO, which results in recurrence of medulloblastomas and metastasis." (PMID 25901736, 2015). "For example, GDC-0449 resistance has occurred in medulloblastoma through a D473H mutation in SMO, which prevented GDC-0449-SMO binding while maintaining aberrant HH signaling." (PMID 26106586, 2015). "It has been shown that the SMO inhibitor cyclopamine can lead to regression of medulloblastoma deficient in patched." (PMID 24586203, 2014). "This type of signaling has been observed in basal cell carcinoma (PTCH and SMO mutations), medulloblastoma (PTCH and SUFU mutations), and rhabdomyosarcoma (PTCH and SUFU loss of heterozygosity)." (PMID 24598114, 2014). "Intrinsic resistance to these agents is frequent, and acquired resistance to GDC-0449 following initial response by mutation of SMO has been reported in medulloblastoma." (PMID 23097684, 2012). "Inactivating mutations in PTCH1 or more rarely, activating mutations in SMO have been identified in most sporadic medulloblastomas." (PMID 22349813, 2012). "Activation mutations in SMO have been observed in a recent clinical trial using CDG-0449 in a medulloblastoma patient." (PMID 21698280, 2011). "Intrinsic resistance to SMO inhibitors is frequent, and acquired resistance to GDC-0449 following initial response has been reported in medulloblastoma (heterozygous mutation, Asp->His at aa 473 in SMO)." (PMID 21860067, 2011). "This could have important clinical implications given that cilium loss has been shown to confer SMO inhibitor resistance in SHH medulloblastoma." (PMID 35835507, 2022). "Mutations in PTCH or SMO are also prevalent in basal cell carcinomas, medulloblastomas, and cancers of the esophagus and bladder, and sustained and activated Hh-Gli signaling has led to the development of medulloblastomas in PTCH heterozygous mice." (PMID 34113570, 2021). "As the hub of the HH signaling, SMO mutation was highly enriched in adult medulloblastoma." (PMID 33446260, 2021). "This may be immediately evident for tumors such as medulloblastomas and basal cell carcinomas that frequently show mutations in either SMO or PTCH1 genes." (PMID 34638386, 2021). "Furthermore, recently PTCH2 and possibly also SMO mutations have been described as a potential cause for Gorlin syndrome associated medulloblastoma." (PMID 34888241, 2021). "Despite the high efficacy of SMO inhibition in patients with basal cell carcinoma and medulloblastoma, which are characterized by the presence of Hh mutations, the efficacy of these inhibitors in ligand-dependent Hh-activated cancer types such as PCa has not yet been established." (PMID 28208838, 2017). "The use of SMO inhibitors has been associated with the acquisition of resistance to SMO inhibitors, mostly described in medulloblastoma, as a consequence of (i) mutations in human SMO (D473H) and the matching mutation in mouse (D477G), observed during vismodegib treatment (Ref." (PMID 25660620, 2015). "Hence, the treatment of mice harboring SMO-mutated SHH-activated medulloblastomas with PLX5622, an inhibitor of the colony-stimulating factor 1 receptor (CSF1R), resulted in a reduced proportion of TAMs in the tumor microenvironment, shrinkage in tumor sizes, and prolonged survival of the mice." (PMID 37568705, 2023). "Importantly, DYRK1B targeting abolished GLI1 expression in SMO-inhibitor sensitive and SMO-inhibitor resistant cells including SUFU deficient medulloblastoma, GLI1-dependent pancreatic cancer and Ewing sarcoma cells expressing GLI1 in response to the EWS-FLI1 oncoprotein." (PMID 26784250, 2016).
medulloblastoma (continued). "In the medulloblastoma, we observed 45 tumor‐specific pathogenic variants in 35 CNS tumor‐related genes, including PTCH1, PTCH2, and SMO, which are frequently altered in medulloblastomas." (PMID 40880425, 2025). "Ablation of primary cilia by Kif3a or Ift88 deletion prevented the growth of medulloblastoma tumours in animal models which was induced by a constitutively active SMO." (PMID 39234399, 2024). "In particular, the DYRKi inhibitor efficiently repressed SMO-dependent Gli1 and SMO-independent Gli1 expression in human medulloblastoma cells (DAOY)." (PMID 38675189, 2024). "For cases with paired tumor and CSF cfDNA WES (n = 15), a mean of 83 (range 1–160) shared SNVs were observed, including SNVs in classical medulloblastoma genes such as SMO and KMT2D." (PMID 37444642, 2023). "The CDK7 inhibitor, TZH1, has shown significant potency in suppressing the SHH-mediated proliferation of medulloblastoma cells, including those that are resistant to SMO inhibitors." (PMID 37568705, 2023). "Herein, cyclopamine is the earliest SMO inhibitor investigated in the context of SHH-activated medulloblastoma, and it acts by binding to the transmembrane portion of the receptor." (PMID 37568705, 2023). "ATO, a GLI antagonist, blocks GLI protein function and when combined with the SMO inhibitor, itraconazole, it effectively overcomes the resistance to SMO inhibition seen in models of medulloblastoma and BCC." (PMID 38020914, 2023). "On the other hand, the antifungal itraconazole inhibits the activity of SMO through halting its translocation to the cilium, and it appears to be effective against D477G-mutant medulloblastoma mouse models that are resistant to other SMO antagonists." (PMID 37568705, 2023). "Arsenic trioxide effectively suppressed tumors with abnormal Hh activation, such as primary medulloblastoma, vismodegib-resistant medulloblastoma and Ewing sarcoma in vivo when used alone or in combination with SMO inhibitor." (PMID 37213270, 2023). "When medulloblastoma was driven by SMO, PC removal will inhibit tumor formation, whilst PC removal was required for tumor growth when the tumor was driven by GLI." (PMID 37101292, 2023). "Sonic hedgehog subtype medulloblastoma is featured with overactivation of hedgehog pathway and can be targeted by SMO‐specific inhibitors." (PMID 35419951, 2022). "Another FDA-approved SMO inhibitor sonidegib was also evaluated in relapsed medulloblastoma in a phase 1/2 trial, with both adult and pediatric patients." (PMID 36010607, 2022). "In human medulloblastoma, mutations in PTCH1, SMO, and SUFU, and amplifications of SHH, GLI2, and MYCN, a pathway target gene, have been identified." (PMID 36010600, 2022). "Mutation of SMO 535 Tryptophan (W) into Leucine (L) (SMOW535L) leads to constitutive activation of SMO and has been found as oncogenic driver mutations in medulloblastoma and basal cell carcinoma." (PMID 35419951, 2022). "Expression of the G12V mutation of pro-oncogene HRAS or HRAS (G12V) and V600E mutations of BRAF induced resistance to SMO inhibitors, such as sonidegib, vismodegib, and LEQ-506, in Shh-subtype medulloblastoma (SMB) cells." (PMID 35163655, 2022). "In medulloblastoma, loss of cilia mediated due to ablation of OFD1 can lead to smoothened (SMO) inhibitor treatment resistance and formation of “persister-like” states that support tumor recurrence." (PMID 35359402, 2022). "Some early clinical trials have shown efficacy of the SMO inhibitor vismodegib in recurrent SHH medulloblastoma phase I trials." (PMID 36249063, 2022). "The importance of bona fide preclinical modeling is underscored by our finding that early embryonic CGNPs, the putative cells-of-origin for infant SHH medulloblastoma, are less sensitive to SMO inhibition." (PMID 35535520, 2022). "Adult SHH-medulloblastoma have frequent upstream pathway alterations (PTCH1 and SMO mutations), but infrequent downstream alterations (SUFU, MYCN amplifications)." (PMID 36249063, 2022).